CHTF8 (chromosome transmission fidelity factor 8)
Description:
Chromosome cohesion factor involved in sister chromatid cohesion and fidelity of chromosome transmission. Component of one of the cell nuclear antigen loader complexes, CTF18-replication factor C (CTF18-RFC), which consists of CTF18, CTF8, DSCC1, RFC2, RFC3, RFC4 and RFC5. The CTF18-RFC complex binds to single-stranded and primed DNAs and has weak ATPase activity that is stimulated the presence of primed DNA, replication protein A (RPA) and proliferating cell nuclear antigen (PCNA). The CTF18-RFC complex catalyzes the ATP-dependent loading of PCNA onto primed and gapped DNA. It also interacts with and stimulates POLH, which is suggestive of a protein network that coordinates DNA repair, recombination and chromosome cohesion reactions with replication fork progression.
Synonyms: CTF8; FLJ20400
Tractability: PROTAC: ubiquitination databases record sites on it; its protein half-life has been measured.
Gene: Protein-coding gene on chromosome 16 (69,118,010 to 69,132,588, reverse strand). Ensembl gene ENSG00000168802.
Subcellular location: Nucleus
Pathways (Reactome):
Cell Cycle: Polymerase switching on the C-strand of the telomere
Gene Ontology:
Molecular function: DNA clamp loader activity; protein binding; single-stranded DNA helicase activity
Biological process: positive regulation of DNA-directed DNA polymerase activity; DNA replication; mitotic sister chromatid cohesion
Cellular component: Ctf18 RFC-like complex; nucleus; nucleoplasm
Genetic constraint (gnomAD): Loss-of-function variants: 6 observed, 11.32 expected, observed/expected ratio (o/e) 0.53, 90% interval 0.29 to 1.05. The upper end of that interval is the gene's LOEUF score, 1.05, which puts it in group 4 of 6, group 1 being the genes least tolerant of losing a copy. Missense variants: 140 observed, 161.33 expected, observed/expected ratio (o/e) 0.87, 90% interval 0.76 to 1. Synonymous variants: 53 observed, 63.81 expected, observed/expected ratio (o/e) 0.83, 90% interval 0.67 to 1.04.
Homologues: Orthologues: chimpanzee CHTF8 (99% identical), rabbit CHTF8 (95% identical), mouse Chtf8 (92% identical), zebrafish chtf8 (66% identical), tropical clawed frog chtf8 (64% identical), Drosophila melanogaster CG34001 (43% identical), Caenorhabditis elegans ctf-8 (26% identical).
Diseases named in the same sentence as CHTF8 in open-access papers:
CHTF8 is named in the same sentence as 2 diseases in open-access papers, as found by Europe PMC text mining. Sharing a sentence is not in itself a finding about the gene and the disease. The quoted sentences say what the papers report.
cancer (2 papers, 2013 to 2023). A tumor composed of atypical neoplastic, often pleomorphic cells that invade other tissues. "All pair-wise combinations between the three “central” synthetic lethal partner genes, WDHD1, FEN1, and CHTF8, and the ten outer cancer-mutated CIN genes were evaluated for synthetic lethality." (PMID 23382697, 2013). "In line with such a functional relationship, POLE3, POLE4, DSCC1, CHTF18, and CHTF8 show a high correlation in co-essentiality score across cell lines as determined by the Cancer Dependency Map database." (PMID 36622344, 2023).
CHTF8 also shares sentences with these, for which no sentence is quoted: colon cancer (1 paper).